CAV1 (caveolin 1)
Diseases named in the same sentence as CAV1 in open-access papers (continued):
Sharing a sentence is not in itself a finding about the gene and the disease.
Hypertension (continued). "It is currently established that Cav-1 competitively inhibits eNOS, but this is not the sole mechanism responsible for the pathogenesis of hypertension or the primary cause of BBB damage." (PMID 40305173, 2025). "Studies reported that CAV-1 might have a role in the impairment of endothelial function, which is a fundamental anomaly in the development of hypertension, atherosclerosis, and coronary artery disease." (PMID 39104759, 2024). "In this study, we confirmed that caveolin-1 is expressed at significantly higher relative levels in neutrophils from patients with hypertension (HTN) compared to neutrophils from normotensive individuals (NTI) (1.22 ± 0.071 vs. 1.05 ± 0.068; p = 0.0391) with the band detected at ∼24 kDa." (PMID 38732158, 2024). "Their findings suggest that targeting the caveolin-1/Notch1 signaling pathways could offer promising therapeutic avenues for hypertension management." (PMID 38067108, 2023). "We have investigated the role caveolae/caveolin-1 (Cav-1) plays in endothelial nitric oxide synthase (eNOS) activation and how it impacts pregnancy-induced decreased vascular reactivity in normotensive (Wistar rats) and spontaneously hypertensive rats (SHR)." (PMID 34858211, 2021). "Interestingly, losartan markedly increased proximal tubular caveolin 1, suggesting that intrarenal angiotensin II is involved in the negative regulation of caveolin 1 during the development of hypertension and renal injury in SHR." (PMID 34831368, 2021). "Thus, H2O2 overproduction can be important to reduce Cav-1 levels and to disrupt the function of caveolae in hypertension." (PMID 33519523, 2020). "Furthermore, SHR rats showed significant loss of caveolin-1 protein levels and induction of iNOS and GFAP levels compared with WKY rats, which suggests that hypertension aggravates inflammatory damage after cerebral ischemic injury." (PMID 24961257, 2012). "Whether upregulation of caveolin-1 in smooth muscle cells and in endothelial cells could serve to induce hypertension warrants further investigation." (PMID 17986358, 2007). "Finally, in addition to this particular effect, there is a direct effect on vasomotor tone (i.e., BPC 157 counteracts both L-NAME-induced hypertension and L-arginine-induced hypotension, and there is a specific activation of Src-Caveolin-1-endothelial nitric oxide synthase (eNOS) pathway." (PMID 34203464, 2021). "Furthermore, Cav-1 deletion prevents transactivation of hypertensive vascular remodeling and contributes to increased mitochondrial ROS levels in a model of AngII-induced hypertension." (PMID 33519523, 2020). "The coordinated expressional changes in eNOS and its allosteric regulator cav-1 may be viewed as a compensatory mechanism to maintain the production of bioactive nitric oxide in the face of developing LV hypertrophy in the setting of arterial hypertension." (PMID 25766467, 2015). "However, changes in common to caveolin-1 expression and G protein signalling, through attenuation of Rgs2 and Rgs5, may contribute to hypertension through augmentation of vasoconstrictor pathways and provide potential targets for common drug development." (PMID 17986358, 2007). "Hypertension induced by AngII in Cav-1 knockout mice does not develop vascular remodeling, which means that Cav-1 deletion attenuates vascular hypertrophy and perivascular fibrosis." (PMID 33519523, 2020). "Polymorphisms including apolipoprotein L1 (APOL1), ATP-Binding Cassette Subfamily B Member 1 (ABCB1), Caveolin 1 (CAV1), and ATP-Binding Cassette Subfamily C Member 2 (ABCC2) have been shown to affect graft survival, hypertension, and calcineurin-induced nephrotoxicity." (PMID 28507980, 2017).
lung adenocarcinoma (36 papers, 2007 to 2024). A carcinoma that arises from the lung and is characterized by the presence of malignant glandular epithelial cells. "The Cav1 P132L mutation was found in two lung adenocarcinomas, only one of which retained the mutation at the metastatic site." (PMID 26315660, 2015). "Furthermore, gemcitabine-based chemotherapy resistance has been associated with high expression of caveolin-1 in lung adenocarcinoma." (PMID 39403603, 2024). "It has recently been demonstrated that CAV1 as well as PPARG are associated with a favorable outcome in lung adenocarcinoma, while the cytokine CXCL2 might be a predictor for immunotherapy response." (PMID 34831349, 2021). "Overexpression of CAV1 can significantly inhibit the proliferation rate of lung adenocarcinoma cells." (PMID 39165641, 2024). "Cav1 is suggested to act as a tumor suppressor in various cancers, including lung adenocarcinoma, by regulating cell proliferation and cell death." (PMID 37513116, 2023). "Meanwhile, key genes extensively indicated significant prognostic significance, and CBX7, ITGA8, ADRB2, and CAV1 were significant favorable factors for lung adenocarcinoma." (PMID 37123398, 2023). "On the other hand, in cutaneous SCC, esophagus, and lung adenocarcinomas, caveolin-1 seems to play an inhibitory role." (PMID 33037799, 2021). "A high expression of Cav-1 was observed in metastatic cancer, while a low expression of Cav-1 has been significantly related with overall survival in lung adenocarcinomas, thus proposing Cav-1 as a notable therapeutic target for cancer treatment." (PMID 33920031, 2021). "Given that the reduction of CAV1 was not significantly correlated with postsurgical recurrence of patients with stage I lung adenocarcinoma, CAV1 is unsuitable as a coordinated molecule to improve the predictive power of EFHD2." (PMID 29097801, 2017). "From the IPA network analysis of microarray results, the increase of CAV1 has a crucial role to induce apoptois of lung adenocarcinoma with cordycepin-treatment." (PMID 28099944, 2017). "In GSE27716, a borderline statistical difference was found in the comparison of CAV1 mRNA levels in noninvasive lung adenocarcinoma patients and invasive lung adenocarcinoma patients (P=0.08)." (PMID 29190968, 2017). "In lung adenocarcinoma cells, Cav-1 is sufficient to promote filopodia formation, cell migration and increase metastatic potential." (PMID 29221162, 2017). "Compared with lung epithelial cell, one study showed that the expression of CAV1 was reduced in lung adenocarcinoma cell lines." (PMID 29190968, 2017). "We performed the same experiment in A549 cells, a human lung adenocarcinoma epithelial cell line, and obtained similar results: cells that were transduced with the CAV1 K176R mutant were more viable than wild-type CAV1- or vector-transduced cells." (PMID 26843476, 2016). "Up-regulation of cav-1 mRNA expression in lung adenocarcinoma (AC) (29.7%) was higher than that observed in lung squamous cell carcinoma (SCC) (15.8%)." (PMID 22200856, 2012). "Consistent with a role for caveolin-1 in migration, re-expression of caveolin-1 in lung adenocarcinoma cells is sufficient to promote filopodia formation, cell migration and metastatic potential of these cells." (PMID 18400052, 2008). "Caveolin-1 levels were also low in tissue samples from primary lung adenocarcinomas, while caveolin-1 levels were generally higher in metastatic tumours." (PMID 18949068, 2007). "Gastric cancer patients who express caveolin-1 have been shown to have poor progression-free survival, and its expression has been found to contribute to tumor progression and metastasis in lung adenocarcinoma cell lines, with a positive correlation with the tumor stage." (PMID 39403603, 2024). "Interestingly, increased Cav1 expression in lung adenocarcinoma has been reported to attenuate H2O2 production favoring tumor progression." (PMID 38473215, 2024).
lung adenocarcinoma (continued). "CAV1 is lower expressed in lung adenocarcinomas and has likewise prognostic potential." (PMID 26930711, 2016). "In lung adenocarcinoma, ROR1 acts as a scaffold for cavin-1 and caveolin-1 (CAV1), two proteins critical for caveolae formation and function." (PMID 39769452, 2024). "We therefore analyzed the CPTAC protein dataset for DLC1, Caveolin-1 and PLCD1 expression in lung adenocarcinoma and lung squamous cell carcinoma compared to adjacent normal lung." (PMID 34727930, 2021). "Moreover, when categorizing patients with stage I lung adenocarcinoma (n = 38), we observed that IB stage LUAD tissues (n = 15) exhibited the highest level of caveolin-1 expression as compared to IA2 (n = 9) and IA3 stage LUAD tissues (n = 14)." (PMID 37996944, 2023). "However, as revealed by a cell proliferation assay, the over-expression of DCN and CAV1 markedly suppresses NSCLC cell proliferation, its role in invasion and migration of lung adenocarcinoma needs further study." (PMID 33870858, 2021). "These include the up-regulation of growth promoting genes such as aldehyde dehydrogenase 1A1 (ALDH1A1) and caveolin-1 (CAV1), and down-regulation of growth suppressing genes like the tumor suppressor 4.1B/differentially expressed in adenocarcinoma of the lung-1 (DAL-1)." (PMID 22591718, 2012). "Similarly, it’s reported that high Cav-1 expression also indicates a better overall survival (OS) for lung adenocarcinoma but not for squamous cell lung carcinoma." (PMID 31901898, 2020).
non-small cell lung carcinoma (36 papers, 2012 to 2025). A group of at least three distinct histological types of lung cancer, including non-small cell squamous cell carcinoma, adenocarcinoma, and large cell carcinoma. "Caveolin 1 has been associated with chemo- and radioresistance in various tumors, including non-small-cell lung cancer." (PMID 26315660, 2015). "CAV1 overexpression has been shown to be associated with drug resistance in non-small cell lung cancers and was reversed in oral squamous cell carcinoma." (PMID 26039373, 2015). "Among these, a plasma membrane-associated protein caveolin-1 (Cav-1) has gained a considerable attention, since its expression has been linked to the advanced stages of squamous and non-small cell lung cancers." (PMID 24939878, 2014). "Cav1 expression has also been shown to be significantly associated with poor prognosis and drug resistance in advanced non-small cell lung cancer patients after treatment with gemcitabine." (PMID 23521716, 2013). "Therefore, in order to further analyze the role of this gene, Chinese non-smoking females were selected as the research subjects to investigate the relationship between CAV1 rs3779514 and susceptibility and prognosis of non-small cell lung cancer." (PMID 39165641, 2024). "In human non-small cell lung carcinoma cells (NCI-H460), vanillin effectively inhibited metastatic potential by down-regulating the expression of caveolin-1 (Cav-1), a protein associated with tumor progression." (PMID 41590042, 2025). "For example, the interaction between Caveolin-1 (Cav-1) and Parkin in non-small-cell lung cancer cells bolsters resistance to cisplatin by encouraging the clearance of damaged mitochondria." (PMID 39859167, 2025). "In non-small-cell lung-cancer patients treated with gemcitabine chemotherapy, CAV1 immunopositivity was shown to be an independent prognostic indicator that predicts for poor disease-free survival and overall survival of patients." (PMID 35158857, 2022). "Caveolin-1 (Cav-1)/Parkin-mediated mitophagy contributes to the resistance of the non-small cell lung cancer cell line A549 to cisplatin." (PMID 34225732, 2021). "We investigated the relationship between Cav-1 expression and non-small cell lung cancer (NSCLC) progression in the context of brain metastasis (BM)." (PMID 31297035, 2019). "Functional assays further revealed that K176R mutant of CAV1 in cancer cells increased the transport activity of P-glycoprotein and decreased the killing ability of anti-cancer drugs in non-small-cell lung cancer cell lines." (PMID 26843476, 2016). "A different group showed that the number of caveolae increased upon stable expression of Cav1-P132L in H1299 cells, a cell line derived from human non-small cell carcinoma that endogenously expresses wild type Cav1." (PMID 27446919, 2016). "Here, caveolin 1 expression was assessed in a series of 69 brain metastases from non-small-cell lung cancer and matched primary tumors to determine its role in predicting survival and radiotherapy responsiveness." (PMID 26315660, 2015). "However, the cav-1 mRNA/protein expression levels in lung tumor tissues (TT) compared to surrounding normal tissues and the association with clinicopathological factors in non-small cell lung cancer (NSCLC) is unknown." (PMID 22200856, 2012). "Finally, weighted gene co-expression network analysis displayed that CAV1 was closely related to the occurrence of non-small cell lung cancer." (PMID 39165641, 2024). "Furthermore, CAV1 enhanced sensitivity to anti-diabetic drug (metformin) in a study comparing two non-small-cell lung cancer cell lines, Calu-1 and Calu-6, which express high and low CAV1 levels, respectively." (PMID 27852311, 2016). "However, the distribution of cav-1 in non-small cell lung cancer (NSCLC) and its significance require further study." (PMID 22200856, 2012).
non-small cell lung carcinoma (continued). "In the present study, we found that the post-translational modification site of CAV1 at lysine 176 influenced the formation of CAV1 oligomers and the interaction between CAV1 and P-glycoprotein, which also affected the transport activity of P-glycoprotein in non-small-cell lung cancer cell lines." (PMID 26843476, 2016). "Overall, caveolin 1 expression in brain metastasis from non-small-cell lung cancer is independently predictive of worse outcome and radioresistance and could become an additional tool for personalized therapy in the critical subset of brain-metastatic non-small-cell lung cancer patients." (PMID 26315660, 2015). "It promotes metastasis in non-small cell lung cancer (NSCLC) by enhancing O-GlcNAcylation and stabilizing key oncogenic proteins such as c-Myc and caveolin-1." (PMID 40806720, 2025). "Caveolin-1, the main component of caveolae, forms a functional complex with DLC1 in non-small cell lung cancer cells by interacting with a region whose binding is reduced by deletion of aminoacids 929 to 957 in DLC1-START." (PMID 34727930, 2021). "Additionally, in non-small cell lung carcinoma cell culture and in an in vivo model, increased glucose uptake with the involvement of GLUT3 and caveolin 1 (Cav1), an important component of lipid rafts, triggered tumor progression and metastasis." (PMID 32252351, 2020). "Additionally, the AMPK activator metformin required Cav-1 to induce AMPK phosphorylation and an AMP/ATP ratio increase in non-small-cell lung cancer." (PMID 26431273, 2015). "H1299 cells are a line of non-small cell lung carcinoma cells that lacked detectable cavin-3, but exhibited levels of cavin-1, caveolin-1, myosin-1c and actin that were similar to the endogenous levels of SV589 fibroblasts." (PMID 24069528, 2013).
lipodystrophy (35 papers, 2008 to 2025). "CAV1 is a protein-coding gene linked to several disorders, including cancer, lipodystrophy, and cardiovascular diseases." (PMID 40332409, 2025). "Congenital generalized lipodystrophy Type 3, associated with mutations in CAV1, exhibits variable clinical presentations, including mild lipodystrophy and less severe metabolic complications." (PMID 39791064, 2024). "More studies are required to unravel the role of distinct CAV1 pathogenic variants in different types of congenital lipodystrophies, such as CGL3, FPLD7, and the neonatal onset of generalized lipodystrophy." (PMID 36354755, 2022). "Cav1 mutation in humans is more commonly associated with lipodystrophy, and Cav1 knockout in mice has previously been shown to cause broader metabolic dysfunctions, in addition to a failure to gain weight under a high-fat diet." (PMID 33015095, 2020). "Both caveolin-1 and PPARγ are among the group of proteins in which mutation results in lipodystrophy." (PMID 28420992, 2017). "The first mutation, c.G112T (p.E38X), is linked to lipodystrophy and leads to a complete loss of Cav1 protein expression." (PMID 27446919, 2016). "In conclusion, we report, for the first time, an association of CAV1 dysfunction with a syndrome of severe premature aging and lipodystrophy." (PMID 26176221, 2015). "In this study we have examined the effect of CAV1 deficiency on mouse adipose tissue as a model of human lipodystrophy." (PMID 23049990, 2012). "This gene was an attractive candidate because it had been shown to interact with caveolin-1, whose mutations cause lipodystrophy and with caveolin-3, whose mutations cause rippling muscle disease." (PMID 20300641, 2010). "Since only two mutations were found among 60 screened subjects, CAV1 mutations are a very rare cause of lipodystrophy and hypertriglyceridemia." (PMID 18237401, 2008). "Until 2012, the disease with the clearest association with Cav1 mutations had been lipodystrophy, although associations between caveolae function and disease had been drawn for multiple other conditions, including cancer, muscular dystrophy, and cardiovascular disease." (PMID 33015095, 2020). "Interestingly, both caveolin-1 and PPARγ are among the group of proteins in which mutations result in lipodystrophy." (PMID 28420992, 2017). "Furthermore, Cav1 and other caveolins have been implicated several pulmonary and vascular diseases, myopathies, lipodystrophies, and cancers." (PMID 27446919, 2016). "Intrinsic tissue instability could impact on both the development of an inflammatory state and, in the case of CAV1 deficiency, the development of lipodystrophy." (PMID 23049990, 2012). "As in vitro-differentiated adipocytes derived from CAV1−/− MEFs do not show the loss of prolipolytic signalling observed in adipose tissue of CAV1−/− mice this suggests that tissue specific perturbations underlie the dysfunction of adipose tissue in CAV1-related lipodystrophies." (PMID 23049990, 2012). "Thus the multi-facetted symptoms of our patients combine the features seen in individuals with mutations in caveolin-1 (lipodystrophy) and in caveolin-3 (myopathy)." (PMID 20300641, 2010). "Thus, very rare CAV1 frameshift mutations appear to be associated with atypical lipodystrophy and hypertriglyceridemia." (PMID 18237401, 2008). "Heterozygous null CAV1 pathogenic variants were also identified de novo in two patients from Europe, with generalized fat loss, thin mottled skin, and progeroid features at birth, with associated lipodystrophy heterozygous CAV1 frameshift mutations also reported." (PMID 40565151, 2025). "On the other hand, suppression of these pathways through reduction or knockdown of some components of the CD59/MMP14/CAV1 axis can lead to enhanced autolysis of adipocytes and is typical in a local lipodystrophy." (PMID 41316800, 2025). "CAV1 (caveolin-1) functions to physically co-localize BMP receptors, and is associated with both lipodystrophy and PAH." (PMID 34900561, 2021).